DRC11 (dynein regulatory complex subunit 11)
Description:
Component of the nexin-dynein regulatory complex (N-DRC), a key regulator of ciliary/flagellar motility which maintains the alignment and integrity of the distal axoneme and regulates microtubule sliding in motile axonemes.
Synonyms: IQCA; IQCA1; FLJ22527; 4930465P12Rik
Tractability: Small molecule: a structure with a bound ligand is known.
Gene: Protein-coding gene on chromosome 2 (236,324,147 to 236,507,716, reverse strand). Ensembl gene ENSG00000132321.
Subcellular location: Cytoplasm, cytoskeleton, flagellum axoneme
Subcellular location (Human Protein Atlas): Flagellar centriole; Primary cilium; Primary cilium tip; Vesicles
Gene Ontology:
Molecular function: ATP hydrolysis activity; microtubule severing ATPase activity; ATP binding
Biological process: cilium movement; flagellated sperm motility; microtubule severing
Cellular component: axonemal nexin link; axoneme
Genetic constraint (gnomAD): Loss-of-function variants: 35 observed, 69.21 expected, observed/expected ratio (o/e) 0.51, 90% interval 0.38 to 0.67. The upper end of that interval is the gene's LOEUF score, 0.67, which puts it in group 2 of 6, group 1 being the genes least tolerant of losing a copy. Missense variants: 696 observed, 776.7 expected, observed/expected ratio (o/e) 0.9, 90% interval 0.84 to 0.95. Synonymous variants: 271 observed, 279.19 expected, observed/expected ratio (o/e) 0.97, 90% interval 0.88 to 1.07.
Homologues: Orthologues: chimpanzee IQCA1 (99% identical), macaque IQCA1 (95% identical), dog IQCA1 (79% identical), guinea pig IQCA1 (79% identical), rat Iqca1 (78% identical), pig IQCA1 (77% identical), mouse Iqca1 (76% identical), rabbit IQCA1 (74% identical), tropical clawed frog iqca1 (60% identical), Drosophila melanogaster CG16789 (36% identical), Drosophila melanogaster CG14183 (27% identical), zebrafish iqca1 (24% identical). Paralogues in human: DRC11L (47% identical).
Diseases named in the same sentence as DRC11 in open-access papers:
DRC11 is named in the same sentence as 4 diseases in open-access papers, as found by Europe PMC text mining. Sharing a sentence is not in itself a finding about the gene and the disease.
DRC11 shares sentences with these, for which no sentence is quoted: Breast Invasive Carcinoma (1 paper); epilepsy (1); neurological disease (1); Venous thrombosis (1).